MET (MET proto-oncogene, receptor tyrosine kinase)
Diseases named in the same sentence as MET in open-access papers (continued):
Sharing a sentence is not in itself a finding about the gene and the disease.
lung cancer (continued). "Further studies on RCCs with prior antiangiogenic therapy have to investigate if MET amplification is seen in therapy resistant RCCs, resembling a resistance mechanism evident in lung cancers with EGFR activating mutations treated with Gefitinib." (PMID 27894094, 2017). "MET amplification (MET/CEP7 ratio ≥5) is a rare independent finding in lung cancer (<0.5%) but is also associated with MET inhibitor sensitivity." (PMID 29050231, 2017). "Our results thus demonstrate that a juxtamembrane mutation of MET can promote its proteolytic cleavage in lung cancer cells leading to generation of an active fragment." (PMID 28061464, 2017). "A number of agents have shown activity in patients with MET-activated lung cancers, such as crizotinib, cabozantinib and capmetinib in patients with tumoral exon 14 skipping mutations and/or MET amplification." (PMID 29050231, 2017). "Additional mutations have been identified in the MET sema domain in lung cancer, and are associated with HGF binding and receptor dimerization." (PMID 27013592, 2016). "Recently variants in MET have been reported to be associated with the prognosis of various human cancers, such as lung cancer and gastric cancer." (PMID 27813498, 2016). "Lung cancer cells expressing this mutation have been reported to be less sensitive to c-MET inhibition by SU11274." (PMID 26009992, 2015). "In lung cancer, various mutations in both the juxtamembrane domain and the extracellular domains of MET, along with MET amplification, are known to activate the receptor and stimulate the PI3K/AKT signaling." (PMID 25962919, 2015). "Both EGFR and c-MET are RTKs that have been implicated in tumor progression as regulators of miRNA cluster 23a/27a~24-2 in lung cancer, in which miR-27a can regulate both c-MET and EGFR." (PMID 26273639, 2015). "Up to 20% of EGFR-mutated lung cancers that have developed acquired resistance to TKIs also exhibit MET amplification in this setting." (PMID 26517520, 2015). "Such ethnical differences have been described for various relevant molecular cancer features, including HER2 amplification in breast cancer, TMPRSS2-ERG gene fusion in prostate cancer, and MET mutation in lung cancer." (PMID 26555375, 2015). "Despite such tight control, aberrant c-MET signaling has been implicated in several malignancies, including lung cancer." (PMID 25925948, 2015). "In nonsmall cell lung cancer, amplification of MET is associated with resistance to gefitinib, the reversible EGFR tyrosine kinase inhibitor, via ErbB3 activation." (PMID 24500024, 2014). "In lung cancer, MET mutations are rare, but amplification is seen in up to 21%, resulting in constitutive MET activation and is believed to be a potential mechanism of acquired EGFR TKI resistance." (PMID 25505733, 2014). "Since there is a relationship between ethnic differences and MET mutations, greater knowledge of this correlation can help us understand incidence, prognosis and treatment of lung cancer." (PMID 27234388, 2013). "Gefitinib-resistant lung cancer cells having high levels of miR-21, miR-30b/c and miR-221/22, as consequence of c-MET overexpression, were rendered susceptible to gefitinib when treated with SU11274, a c-MET inhibitor." (PMID 24349829, 2013). "EGFR gene mutations, KRAS gene mutations, EML4-ALK rearrangements and altered MET signaling are widely recognized alterations that play important roles in both the biological mechanisms and the clinical sensitivity to treatment in lung cancer." (PMID 27234388, 2013). "MET amplification in lung cancer has recently been shown to be associated with activation of EGFR, ERBB2, ERBB3, and RET." (PMID 23300999, 2013). "MET amplification was also observed at a low frequency in EGFR mutant lung cancers in patients prior to treatment and was associated with the development of acquired resistance to EGFR TKIs." (PMID 22970367, 2012).
lung cancer (continued). "The prevalence of c-MET mutations is relatively low compared to the frequency of c-MET overexpression in lung cancer, but their potential for causing disease progression has been shown to be significant." (PMID 22363766, 2012). "Next, associations of the ‘anti-EGFR/MET’ lipid metabolism genes with other genes were evaluated by calculation of the intergene Pearson correlation coefficients in lung cancer samples." (PMID 22211244, 2012). "Amplification of MET occurs in ∼4% of lung cancer patients, with activation of MET signalling being associated with advanced cancer stage and shorter patient survival." (PMID 21847121, 2011). "It is important to note, we have recently shown that MET mutations in lung cancer are in majority germline." (PMID 20126411, 2010). "This strongly suggests that in lung cancer, global patterns of tyrosine phosphorylation are at least as dependent on MET activation as they are on EGFR mutation." (PMID 20976048, 2010). "The c-MET/HGF pathway has gained considerable interest through its apparent deregulation by overexpression or gain-of-function mutations in c-MET in various cancers, including lung cancer." (PMID 17667909, 2007). "We generated an oncoprint of the top 25 mutated genes among lung cancer cohort with MET mutations." (PMID 41521799, 2026). "The MET exon 14 skipping mutation (named METex14Del) described in lung cancer leads to prolonged activation of signaling pathways and aberrant cell responses, but the link between HGF signaling and cell responses remains unclear." (PMID 41184222, 2025). "While we identified that MET IHC expression may serve as a predictive marker for the efficacy of ICIs in lung cancer, the underlying mechanisms and its correlation with PD-L1 expression have not been thoroughly investigated and warrant further research." (PMID 41375002, 2025). "Additionally, lung cancers with MET exon 14 skipping mutations exhibit distinct characteristics in the immune microenvironment." (PMID 40710213, 2025). "The first reports of MET exon 14 mutations came from primary lung cancer samples and cell lines." (PMID 40361420, 2025). "It has been previously indicated that aberrations in MET signaling may be associated with a worse prognosis in lung cancer patients, including those with SCLC." (PMID 40649874, 2025). "While MET exon 14-skipping mutations are found in many types of cancer, such as gliomas, gastrointestinal cancers, and sarcomas, they are predominantly found in lung cancers and most commonly in NSCLCs." (PMID 40361420, 2025). "Consistent with the “tissue-first” and “plasma-first” approaches recommended by the International Association for the Study of Lung Cancer, as well as the tepotinib US Prescribing Information, a positive result from either biopsy type can be considered sufficient for MET inhibitor eligibility." (PMID 40310449, 2025). "Tepotinib therapy may be effective for patients with MET exon 14 skipping mutation, including those with G‐CSF‐producing lung cancer." (PMID 38919814, 2024). "In 2014, novel MET mutations were identified in several advanced cancers, including lung cancers." (PMID 38652103, 2024). "Patients with mutations such as KRAS, BRAF and c-MET may benefit from NA ICI-chemo based on the extrapolation of the benefit of immunotherapy in patients with advanced lung cancer who have these mutations." (PMID 38610980, 2024). "In conclusion, G‐CSF‐producing lung tumours can manifest as sterile lung abscesses, and tepotinib therapy may effectively target these tumours in patients with MET exon 14 skipping mutations, even in cases of G‐CSF‐producing lung cancer." (PMID 38919814, 2024). "Only two genes (KRAS and MET) were found to be associated with lung cancer." (PMID 37867380, 2023).
lung cancer (continued). "In fact, in prospective clinical trials, tepotinib, capmatinib, and savolitinib showed high activity in advanced stage lung cancer patients harboring the MET exon 14 skipping mutation, including treatment-naïve patients and those affected by pulmonary sarcomatoid carcinoma." (PMID 36832117, 2023). "MET exon 14 skipping is an oncogenic targetable driver mutation in lung cancer." (PMID 36230737, 2022). "In addition, the results of the AACR-Project, identifying 5.8% of patients with MET mutations and 0.1% with MET amplifications, underlines the low frequency of MET alterations in lung cancers." (PMID 36291897, 2022). "Nonetheless, MET amplification is recognized as a mechanism of resistance following small-molecule inhibitor targeting of EGFR mutant lung cancer, and conversely, EGFR and HER3 amplification or mutation have been observed as resistance mechanisms to Met inhibition in human cancers." (PMID 35249128, 2022). "A collective of 20 formalin-fixed paraffin-embedded lung cancer tissue samples (mean age 64 years) were selected based on increased MET gene copy number (CNV) status or the presence of mutations detected by NGS (GeneReader, QIAGEN) and were further assessed by FISH (MET/CEN7, Zytomed)." (PMID 34733418, 2021). "We have developed a new preclinical mouse model that will help the lung cancer community to develop and test in vivo novel therapeutic options for patients with EGFR-mutated lung cancer who relapse after osimertinib therapy due to the appearance of MET amplification." (PMID 34298655, 2021). "Furthermore, the MET N375S mutation modulates sensitivity and confers resistance to MET inhibitors, eventually suppressing MET inhibitor-mediated apoptosis in lung cancer cells." (PMID 32754598, 2020). "Moreover, new alterations in MET sequence have been recently identified, such as MET exon 14 skipping in lung cancers and the emergence of MET mutations in the kinase domain following treatment with MET inhibitors." (PMID 32093126, 2020). "KIF5B gene and MET gene were reported to fuse in lung cancer, which causes elevated tumor growth." (PMID 33204717, 2020). "Interestingly, one case of a patient with advanced lung cancer with a MET exon 14 skipping mutation and MET exon 5 C526F mutation was reported." (PMID 32435640, 2020). "MET mutations in lung cancer are considered to be predictors of susceptibility to the MET inhibitor crizotinib, whereas RET translocations are correlated with a positive response to targeted therapy with RET inhibitors such as cabozatinib, vandetinib, and alectinib." (PMID 33198090, 2020). "As personalized medicine is currently gaining popularity, our findings for crizotinib may contribute to effective prescriptions to prevent further development of drug-resistant cancer in lung cancer patients who have c-MET and ALK mutation phenotypes." (PMID 32528877, 2020). "Both MET gene amplification and exon 14 skipping mutations are present in all major histologic types of lung cancers, including adenocarcinoma, squamous, adenosquamous, large cell and small cell, but are more frequently found in adenocarcinoma and adenosquamous respectively." (PMID 31369639, 2019). "In view of the importance of MET mutations in the lung cancer pathogenesis and in guiding diagnosis and treatment, the prevalence and clinicopathological features of the two MET alterations are investigated using a lung cancer population of Taiwan in the current study." (PMID 31369639, 2019). "Somatic mutations of MET gene are emerging as important driver mutations for lung cancers." (PMID 31369639, 2019). "Overexpression of MET protein could be frequently observed and is associated with poor prognosis in lung cancer." (PMID 31369639, 2019). "MET mutations are found in 3–10% of lung cancers and mostly affect the juxtamembrane domain." (PMID 28061464, 2017). "The role of MET mutations in lung cancer, seen in up to 7% of adenocarcinomas, remains complex." (PMID 29050231, 2017).
lung cancer (continued). "The receptor tyrosine kinase MET and its ligand, the hepatocyte growth factor, are essential to embryonic development, whereas deregulation of MET signaling is associated with tumorigenesis leading to various cancers, including lung carcinoma." (PMID 28061464, 2017). "Moreover, loss of MET expression also contributed to inhibition of lung cancer cell (both A549 and SK-MES-1 cells) growth and migration." (PMID 26325180, 2015). "In addition to EGFR mutations, MET amplification/over-expression was also reported as another common EGFR TKI resistance mechanism in lung cancer." (PMID 25674538, 2015). "Recent clinical studies have demonstrated that MET amplification predicts that patients with lung cancer and activating EGFR mutations will fail to respond to erlotinib or gefitinib, and KRAS mutation predicts that patients with colon cancer will fail to respond to cetuximab." (PMID 23577104, 2013). "Moreover, one-point mutation of the MET extra-cellular domain (i.e., N375S) was seen in 13% of East Asians with lung cancers." (PMID 23296269, 2013). "Interestingly, a mutliethnic study on 141 asian, 76 Caucasian, and 66 African American lung cancer patients revealed that the type and frequency of MET mutations were different among each group." (PMID 22928112, 2012). "Although MET has been found to associate with other RTKs, the underlying mechanisms and regulation of such association in lung cancer with MET amplification remain largely unclear." (PMID 21847121, 2011). "EMD1214063 is a potent and selective inhibitor of the MET TK receptor with > 1000-fold selectivity for MET compared to other kinases and is in phase 2 clinical trial for patients with confirmed MET exon 14 skipping mutation with advanced or metastatic non–small-cell lung cancer." (PMID 35754026, 2022). "In addition, some studies found that the aberrant expression and activation of MET result in the activation of the ERBB3/PI3K/AKT pathway, which is associated with the resistance of EGFR inhibitors in lung cancer, and this resistance can be reversed by combining MET inhibitors and EGFR inhibitors." (PMID 34761497, 2021). "To develop a mouse model that could recapitulate osimertinib resistance caused by MET amplification in patients with EGFR-mutated lung cancer, we took advantage of a mouse strain in which liver carcinoma develops upon induction of human WT MET expression in the liver." (PMID 34298655, 2021). "Although the small sample size is an inherent limitation of the study, it could help in collecting new data at a faster rate and prompt extending our understanding of MET alterations in lung cancers, such as whether MET exon 14 skipping mutations result in MET protein overexpression or not." (PMID 31369639, 2019). "In the current study, one of the MET exon 14 skipping mutation cases identified from a pulmonary carcinosarcoma, demonstrated such possibility and highlighted the necessity to broaden the screening scope for this mutation in other minority lung cancer subtypes." (PMID 31369639, 2019). "Although MET exon 14 skipping mutations have been identified across different major histological subtypes of lung cancers, whether this mutation is present in other minority subtypes of lung cancers remains unknown." (PMID 31369639, 2019). "Hence, to investigate the finding of clinical results and whether CBL could be a positive indicator for MET-targeted therapeutics in lung cancer, we used the EGFR L858R/T790M mutation cell line H1975." (PMID 28835699, 2017). "Moreover, loss of MET expression also contributed to inhibition of lung cancer cell (both A549 and H1299 cells) growth, migration and invasion, and promotion of cell apoptosis in lung cancer cell (both A549 and H1299 cells)." (PMID 26909600, 2016).
lung cancer (continued). "Indeed, in a targeting/drug delivery perspective some scFvs antibodies were also generated that specifically bind to c-MET protein, as aberrantly expressed c-MET has been implicated in human lung cancer as well as malignancy, metastasis, and drug-resistance in other human cancers." (PMID 22606042, 2012). "Conversely, within the MET Kinase Domain mutation subgroup, the brain tumor cohort exhibited a significantly higher TMB than the lung cancer cohort (p = 0.016)." (PMID 41521799, 2026). "In non‐small cell lung cancer, MET exon 14 skipping and MET amplification confer sensitivity to MET tyrosine kinase inhibitors." (PMID 41521799, 2026). "In recent years, there has been interest in MET exon 14 alterations as potential drivers of lung cancer." (PMID 39773744, 2025). "Crizotinib, an anaplastic lymphoma kinase (ALK)/ROS1/c‐MET inhibitor, improves outcomes in ALK‐positive non‐small cell lung cancer (NSCLC) but can cause crizotinib‐associated renal cysts (CARCs), a rare yet clinically relevant adverse effect." (PMID 40542555, 2025). "According to this threshold, 13 patients with cancer exhibited serum binding to MET: 8 patients with breast cancer (10.6%) and 5 patients with lung cancer (20%) (indicated by red asterisks)." (PMID 40401526, 2025). "For other prevalent actionable mutation in lung cancer KRAS, PIK3CA, FGFR3, MET, NRAS, and RET demonstrated 100 % specificity with varied sensitivities around 50 %." (PMID 40503459, 2025). "A study of 168 cases of lung cancer with skipping of MET exon 14 has demonstrated that 40% of cases are resistant to inhibitors of the MET tyrosine kinase domain." (PMID 40564049, 2025). "Though targeted therapy against MET is possible, resistance to these therapies results in their efficacy being much lower than what is observed for TKIs targeting other RTKs that drive lung cancer progression." (PMID 39858062, 2025). "As savolitinib is a selective MET tyrosine kinase inhibitor that targets MET-driven lung cancer, thus MET alterations were diagnosed at progression using a liquid or tissue biopsy." (PMID 40002158, 2025). "We show that out of the 100 patients analyzed, in 2 heterogeneous subcohorts of patients with breast and lung cancer, 13 had serological binding to MET." (PMID 40401526, 2025). "The other patient did not receive a MET inhibitor due to the rapid deterioration of condition due to lung cancer as the discovery of MET was after third‐line treatment." (PMID 40878657, 2025). "Most recent studies showed that MET fusions occur in multiple solid tumors, but are overall rare, for example, being seen in 0.2% to 0.3% of lung cancers." (PMID 40361420, 2025). "Experimental models of radon-induced lung cancer in rats revealed frequent chromosomal losses in regions homologous to human 7q21–36, where the MET gene is located." (PMID 40427695, 2025). "The VISION trial of tepotinib, a selective MET inhibitor, enrolled patients with non–small cell lung cancer and prospectively detected MET exon 14 (METex14) skipping in liquid biopsies (LBx) and/or tissue biopsies (TBx)." (PMID 40310449, 2025). "Key elements of the MAPK pathway, such as EGFR, RAS, ERK, and MET, are recognized lung cancer therapeutic targets." (PMID 41019373, 2025). "MET is recognized as a tumor antigen in both breast and lung cancers, and its expression correlates with poor prognosis." (PMID 40401526, 2025). "The amplification of KRAS also renders lung cancer cells resistant to crizotinib, a MET inhibitor, by hypersensitizing them to ligand stimulation." (PMID 40312750, 2025). "MAbs targeting HGF or MET have demonstrated significant antitumour potential in non–small-cell lung cancer (NSCLC)." (PMID 40599602, 2025). "Presently, EGFR-TKI resistance in lung cancer arises through various mechanisms, including secondary mutations in EGFR (e.g., T790M), activation of alternative signaling pathways (e.g., MET, HER2), phenotypic transformation (small cell transformation)." (PMID 39744423, 2025).